BRCA2 (BRCA2 DNA repair associated)
Diseases named in the same sentence as BRCA2 in open-access papers (continued):
Sharing a sentence is not in itself a finding about the gene and the disease.
breast cancer (continued). "We estimate that 32% of breast cancer FRR for ER-negative disease is explained by BRCA1 and BRCA2 mutations alone." (PMID 20146796, 2010). "The major breast cancer (BC) predisposing genes, BRCA1 and BRCA2 were identified in 1994 and 1995, respectively." (PMID 20219108, 2010). "A range of regimes was used to treat 27 lymphoblastoid cell-lines (LCLs) derived from affected women in high-risk breast cancer families (nine BRCA1, nine BRCA2, and nine non-BRCA1/2 or BRCAX individuals) and nine LCLs from healthy individuals." (PMID 20174566, 2010). "Some murine Brca2 mutant mammary tumour models develop mammary tumours with histopathological features that are significantly different to their human counterparts." (PMID 20877358, 2010). "Approximately 3% to 5% of all breast cancers and approximately 10% of ovarian cancers are due to inherited mutations in the breast and ovarian cancer susceptibility 1 or 2 genes (BRCA1 or BRCA2)." (PMID 20920338, 2010). "Breast cancers initiated in women who are heterozygous for BRCA1 or BRCA2 often have a reduction to homozygosity at the BRCA-locus eliminating its functions." (PMID 20111735, 2010). "Estimates of breast cancer association for loci (two confirmatory loci at FGFR2 and TOX3, and two novel loci with stage 1 and 2 combined of p<10−4) among BRCA2 mutation carriers in a two-staged genome-wide association study." (PMID 21060860, 2010). "MRI has been shown to be effective in detecting small breast cancers in BRCA1 and BRCA2 mutation carriers." (PMID 19088722, 2009). "Perhaps it is because high-risk women without an identified mutation are, on average, at lower lifetime risk for breast cancer (30–40%) than BRCA1 and BRCA2 mutation carriers (60–80%) and thus the balance of risks and benefits is assessed differently." (PMID 19409108, 2009). "Three of 31 early onset (≤ 35 years) breast cancer cases had deleterious mutation, 2 in BRCA1 (7%) and 1 in BRCA2 (3%) gene." (PMID 19656415, 2009). "The number of mutation carriers who developed breast cancer in this study were very small (8 BRCA1 and 11 BRCA2), so the confidence intervals are wide and the results difficult to interpret." (PMID 19409108, 2009). "In most Western populations, 5–10% of all breast cancer cases can be attributed to major genetic factors such as predisposing mutations in BRCA1 and BRCA2, with early-onset cases generally considered as an indicator of genetic susceptibility." (PMID 19491894, 2009). "Familial breast cancers, including those associated with heterozygous germline mutations in the major susceptibility genes BRCA1 and BRCA2, account for 5–10% of breast cancer cases in the western world." (PMID 19904273, 2009). "More recent studies have reported the frequent occurrence of large genomic BRCA2 rearrangements in male breast cancer families." (PMID 21637503, 2009). "I don't think that there's really strong evidence to support a reduction in breast cancer occurrence [in BRCA1 and BRCA2 mutation carriers]." (PMID 19409108, 2009). "The Breast Cancer Information Core Database (BIC) lists more than 1560 and 1880 mutations and polymorphisms in the BRCA1 and BRCA2 genes respectively." (PMID 19329713, 2009). "For example, it is clear from studies on the hereditary forms of breast cancer that mutations in the BRCA1 and BRCA2 genes are often specific to individual populations." (PMID 19956539, 2009).
breast cancer (continued). "The study included 1,222 BRCA1 carriers (433 diagnosed with breast cancer) and 543 BRCA2 carriers (238 diagnosed with breast cancer)." (PMID 19843326, 2009). "We estimate the lifetime risk of breast cancer in these women to be approximately 40%, or roughly one-half of a BRCA1 or BRCA2 mutation carrier." (PMID 19088722, 2009). "Cumulative breast cancer risks by age 70 are estimated to be 65% for BRCA1 and 45% for BRCA2 mutation carriers." (PMID 19619314, 2009). "About 5%–10% of breast cancer and ovarian cancer are hereditary and 30%–50% of these are due to the autosomal dominant mutations in the susceptibility genes, BRCA1 and BRCA2." (PMID 19594871, 2009). "Among BRCA2 carriers, an LD block in IGFBP2 (global P = 0.0145) was found to be associated with the time to breast cancer diagnosis." (PMID 19843326, 2009). "For women with a significant family history of breast cancer, genetic testing for mutations in BRCA1 and BRCA2 is available throughout Canada and elsewhere." (PMID 19088722, 2009). "This study investigated 3226 gene expression profiles to identify the gene set that can discriminate three types of breast cancer: the BRCA1-mutation, BRCA2-mutation, and sporadic cases." (PMID 19187562, 2009). "In Sardinian breast cancer population, BRCA2 was the most affected gene and the effects of BRCA2 germline mutations on patients' survival were demonstrated to vary within the first two years from diagnosis." (PMID 19232099, 2009). "Rad51 assembly is regulated by the breast cancer suppressor Brca2, via its evolutionarily conserved BRC repeats, and a distinct carboxy (C)-terminal motif whose biological function is uncertain." (PMID 19540122, 2009). "BRCA1 and BRCA2 genes had been identified by linkage analysis and positional cloning on large breast cancer families in the early 1990's." (PMID 19656415, 2009). "We have genotyped rs744154 in 9408 BRCA1 and 5632 BRCA2 mutation carriers from the Consortium of Investigators of Modifiers of BRCA1/2 (CIMBA) and assessed its association with breast cancer risk using a retrospective weighted cohort approach." (PMID 19920816, 2009). "Most of breast cancers are considered sporadic and modulation of the two major genes BRCA1 and BRCA2 expressions caused by tissue-specific somatic mutations lead to this pathology." (PMID 19442290, 2009). "The average cumulative risk of breast cancer in a BRCA1 and BRCA2 mutation carrier is 65% and 45% by the age of 70 years, respectively." (PMID 19656415, 2009). "We use the algorithm for breast cancer related to BRCA1 and BRCA2 mutations, but it can be easily applied to other cancers, provided the penetrance functions of the genes involved are known." (PMID 19563646, 2009). "The two major contributors to hereditary breast cancer are the cancer susceptibility genes BRCA1 and BRCA2." (PMID 19298662, 2009). "In a study of 254 white women from the UK, diagnosed with breast cancer before age 36, a germline BRCA1 or BRCA2 mutation was identified in only 6% (ref 16)." (PMID 19298662, 2009). "BRCA2 is the first CHEK2-modifying gene proposed for breast cancer; however, the relevant BRCA2 allele (T1915M) was rare and was present in only 6% of the population controls and in 11% of the cases of CHEK2-associated breast cancer." (PMID 19401704, 2009). "In this study, we investigate the association of variants in genes involved in IGF signaling and risk of breast cancer in women who carry deleterious BRCA1 and BRCA2 mutations." (PMID 19843326, 2009). "On the basis of this finding, we aimed to assess ERCC4-rs744154 as a breast cancer risk modifier in BRCA1 and BRCA2 mutation carriers." (PMID 19920816, 2009).
breast cancer (continued). "We have found that Amp13q34 is present in around 4.5% of breast cancer samples, although the rate differs slightly among tumor classes, being higher in BRCA1- (8.1%) than in BRCA2- or non-BRCA1/2- (< 3.0%) associated cancers." (PMID 19995430, 2009). "Cancer risk counseling of patients and families with an unclassified variant of the breast cancer (BC) genes BRCA1 and/or BRCA2 (MIM numbers 113705 and 600185, respectively) has become a prominent issue for genetic counselors and oncologists." (PMID 19200354, 2009). "Only two BRCA1 and BRCA2 mutations have been found in the Icelandic population, BRCA2 999del5 and BRCA1 G5193A, both being founder mutations explaining a large proportion of familial breast cancer in Iceland." (PMID 18637200, 2008). "We sequenced BRCA1/BRCA2 in 1,469 population-based female breast cancer patients diagnosed between the ages of 20 and 49 years." (PMID 18284688, 2008). "In the present study of young breast cancer patients, we identified numerous variants in BRCA1/BRCA2 by direct sequencing, including 22 BRCA1 and 30 BRCA2 new variants that have not been reported in the BIC as of April 2007." (PMID 18284688, 2008). "We have previously developed a model (BOADICEA) under which susceptibility to breast cancer is explained by mutations in BRCA1 and BRCA2, as well as by the joint multiplicative effects of many genes (polygenic component)." (PMID 18349832, 2008). "It is possible that the higher overall breast cancer estimates for BRCA2 were related to competing mortality from ovarian cancer." (PMID 18513387, 2008). "For example, Fanconi anemia gene Fancd2 and breast cancer gene Brca2 had a higher expression in testis than in ovary." (PMID 18522719, 2008). "Mutation detection led to the discovery of 27 deleterious mutations in 28 breast cancer patients (14 in BRCA1 and 13 in BRCA2)." (PMID 18627636, 2008). "Extensive breast density is therefore one of the strongest known risk factors for developing breast cancer, second only to age and carrying a BRCA1 or BRCA2 mutation." (PMID 18781174, 2008). "Taken together, the data suggests that the presence of two or more breast cancers with at least one case under the age of 50, and ovarian cancer at any age are significant predictors for the presence of a BRCA1 or BRCA2 mutation." (PMID 18627636, 2008). "In BRCA2 IVS16-2A>G families we found a breast cancer incidence of 24.6% (15/61), which is higher than what is seen in the two types of BRCA1 families." (PMID 18783588, 2008). "The BRCA1 DDCV carriers were substantially more likely to have a first-degree family history of breast cancer or ovarian cancer than the normal/polymorphic BRCA1 carriers (odds ratio = 11.3) after adjusting for the BRCA2 mutation status." (PMID 18284688, 2008). "The morphology of breast cancer found in female BRCA1 and BRCA2 germline mutation carriers has been studied extensively." (PMID 18182994, 2008).
breast cancer (continued). "In the high-risk families that recruited to the Breast Cancer Linkage Consortium (BCLC) cohort, BRCA1 and BRCA2 mutations were estimated to cause a cumulative lifetime risk of breast cancer at age 70 years of 85–87% and 77–84% respectively." (PMID 18513387, 2008). "The mean age at breast cancer diagnosis in BRCA1 mutation carriers was 42.98 years and 48.71 years for BRCA2 mutation carriers, respectively." (PMID 18783588, 2008). "It is commonly assumed that 5–10% of all breast cancer cases can be attributed to a genetic predisposition, of which the breast cancer genes BRCA1 and BRCA2 have been identified as most important." (PMID 18834503, 2008). "Hereditary breast carcinomas are predominantly a consequence of loss-of-function germline mutations in one of two major breast cancer susceptibility genes, BRCA1 and BRCA2." (PMID 18431501, 2008). "Germline mutations in both BRCA2 and CHEK2 are associated with an increased risk for male breast cancer." (PMID 18797466, 2008). "The strongest evidence is for prostate and pancreatic cancer in BRCA2 carriers, which has been consistently found in multiple studies." (PMID 18349832, 2008). "Since the discovery of the BRCA1 and BRCA2 genes, a total of 1,643 and 1,856 distinct variants have been reported in the Breast Cancer Information Core (BIC) Database for BRCA1 and BRCA2 as of April 2007." (PMID 18284688, 2008). "It is noteworthy that in our series the average number of breast cancers (BC) per family was twice as much in BRCA2 families (3.3) as compared to BRCA1 families (1.6)." (PMID 18783588, 2008). "Several genes are known to confer increased susceptibility to breast cancer, including BRCA1 and BRCA2, but it has been estimated that they explain only about 25% of the familial risk and less than 5% of the total breast cancer incidence." (PMID 17997823, 2007). "A significant proportion of inherited breast cancer is caused by mutations in the BRCA1 and BRCA2 tumour suppressor genes which disrupt their role in cellular DNA repair, cell cycle control, apoptosis, and tumour suppression." (PMID 18036263, 2007). "Breast cancers in men are characteristic of the BRCA2 phenotype, which accounts for approximately 15% of all MBC." (PMID 17254323, 2007). "Breast density has been shown to predict risk among women with a genetic predisposition for breast cancer, including women carrying BRCA1 or BRCA2 mutations." (PMID 17949495, 2007). "Certain tumour characteristics are characteristically seen in breast cancers due to a BRCA1 gene mutation and also to a lesser degree in BRCA2 gene carriers." (PMID 17697367, 2007). "Mutation frequencies reported in the literature indicate that about 10% of all women with breast cancer diagnosed before the age of 50 years have a germline mutation in BRCA1, BRCA2, ATM or CHEK2." (PMID 17428320, 2007). "Studies including clinical samples from the UK, The Netherlands, Finland, and Canada have confirmed that, like BRCA2, PALB2 is both a breast cancer susceptibility gene and a Fanconi anemia gene." (PMID 18053174, 2007). "Hereditary ovarian and breast cancers are based on germline mutations in the same cancer susceptibility genes, BRCA1 and BRCA2, suggesting similar pathways of oncogenesis at least for a fraction of these diseases." (PMID 17245339, 2007). "For breast cancer, heterogeneous genetic backgrounds seem to instead account for such deep differences into the BRCA2 gene involvement." (PMID 17640379, 2007). "Cumulative risk for this malignancy was assessed in 164 BRCA2-BCLC families, which included 59 cases of male breast cancer, and risk was estimated at 2.8% (95% CI 0.6–13.0%) by age 70 years, rising to 6.9% by age 80 years (95% CI 1.2–38.6%)." (PMID 17213823, 2007). "An additional recruitment category includes women aged 41 to 50 years who are found to be BRCA1 or BRCA2 gene carriers and were diagnosed with their first breast cancer during the study recruiting period." (PMID 17697367, 2007).
breast cancer (continued). "• The BRCA data contains 3,170 genes and was collected from 15 patients with hereditary breast cancer, who had mutations either of the BRCA1(n = 7) or the BRCA2 gene (n = 8)." (PMID 17257426, 2007). "BRCA1 and BRCA2 can be identified in about half of the breast cancer patients with positive family history." (PMID 17233897, 2007). "Compared to other BRCA2 mutations, OCCR mutations are associated with higher ovarian cancer risk (RR=1.88; 95% CI 1.08–3.33) and lower breast cancer risk (RR=0.63; 95% CI 0.46–0.84)." (PMID 17213823, 2007). "A larger case-only study found that increased physical activity and lack of obesity in adolescence were associated with significantly delayed breast cancer onset in BRCA1 and BRCA2 carriers." (PMID 17213823, 2007). "Several previous studies have evaluated the risk of breast cancer associated with OC use among women with a family history of breast cancer or those carrying germline defects in BRCA1 or BRCA2." (PMID 17553133, 2007). "Numerous advances in our understanding of genetic susceptibility to breast cancer have been made over the past decade, most notably the discovery of BRCA1 in 1994 and BRCA2 in 1995." (PMID 17916242, 2007). "The involvement of altered expression of BRCA2 in the development of sporadic breast cancer is a possibility." (PMID 17945002, 2007). "Among the seven families, 32 members, including 16 probands with histologically-proven diagnosis of breast cancer, were genotyped with markers spanning the BRCA2 locus at chromosome 13q12-q13." (PMID 17640379, 2007). "In the present study, we ascertain the functional role of a common polymorphism -26 G>A (GenBank accession number AY151039, rs1799943) in the 5' untranslated region (UTR) of the BRCA2 gene and test its implications in breast cancer pathogenesis." (PMID 17945002, 2007). "Less than 40% of familial breast cancer can be attributed to mutations in the high-risk genes BRCA1 and BRCA2 despite their high penetrance." (PMID 17697391, 2007). "RAD51 interacts directly or indirectly with a number of proteins implicated in breast cancer, such as BRCA1 and BRCA2." (PMID 16762046, 2006). "Breast cancer risk in the general population is closely related to reproductive history, and reproductive factors are therefore strong candidates for modifiers of breast cancer risk in BRCA1 and BRCA2 mutation carriers." (PMID 17187672, 2006). "Breast cancer predisposition genes identified to date (e.g., BRCA1 and BRCA2) are responsible for less than 5% of all breast cancer cases." (PMID 16672066, 2006). "We now report that both I3C and genistein induce the expression of both breast cancer susceptibility genes (BRCA1 and BRCA2) in breast (MCF-7 and T47D) and prostate (DU-145 and LNCaP) cancer cell types, in a time- and dose-dependent fashion." (PMID 16434996, 2006). "The existence of dominant predisposition alleles/mutations, conferring a high breast cancer risk, has been confirmed with the discovery of BRCA1 and BRCA2." (PMID 16672066, 2006). "A recent meta-analysis of 22 population-based studies of breast and ovarian cancer estimated the risk for breast cancer by age 70 years in BRCA1 and BRCA2 carriers to be 65% and 45%, respectively." (PMID 16417652, 2006). "In particular, increasing parity has been shown to be protective for breast cancer in the general population in many studies, but its effect among BRCA1 and BRCA2 mutation carriers is still under debate." (PMID 17187672, 2006). "Evidence-based screening guidelines are needed for women under 40 with a family history of breast cancer, a BRCA1 or BRCA2 mutation, or other risk factors." (PMID 16800895, 2006).